OSBP (oxysterol binding protein)
Description:
Lipid transporter involved in lipid countertransport between the Golgi complex and membranes of the endoplasmic reticulum: specifically exchanges sterol (cholesterol) with phosphatidylinositol 4-phosphate (PI4P, 1,2-diacyl-sn-glycero-3-phospho-(1D-myo-inositol 4-phosphate)), delivering sterol to the Golgi in exchange for PI4P, which is subsequently degraded by the SAC1/SACM1L phosphatase in the endoplasmic reticulum. Binds cholesterol and a range of oxysterols including 25-hydroxycholesterol. Cholesterol binding promotes the formation of a complex with PP2A and a tyrosine phosphatase which dephosphorylates ERK1/2, whereas 25-hydroxycholesterol causes its disassembly. Regulates cholesterol efflux by decreasing the stability of the relatively short lived ABCA1 protein (an important point of control for cholesterol efflux activity).
Synonyms: OSBP1
Tractability: Small molecule: a structure with a bound ligand is known; a high-quality ligand is known. Antibody: UniProt places it where antibodies can reach, with high confidence; its Gene Ontology location is reachable by antibodies, with medium confidence. PROTAC: ubiquitination databases record sites on it; its protein half-life has been measured; a small molecule that binds it is known.
Gene: Protein-coding gene on chromosome 11 (59,574,398 to 59,615,781, reverse strand). Ensembl gene ENSG00000110048.
Subcellular location: Cytoplasm, cytosol; Cytoplasm, perinuclear region; Golgi apparatus membrane; Endoplasmic reticulum membrane; Golgi apparatus, trans-Golgi network
Subcellular location (Human Protein Atlas): Golgi apparatus; Cytosol; Nucleoplasm
Pathways (Reactome):
Metabolism: Sphingolipid de novo biosynthesis; Synthesis of bile acids and bile salts
Gene Ontology:
Molecular function: lipid transfer activity; phosphatidylinositol-4-phosphate binding; phosphatidylinositol-4-phosphate-cholesterol exchange activity; protein binding; protein domain specific binding; sterol transfer activity; oxysterol binding; lipid binding; small molecule binding; sterol binding
Biological process: ceramide transport; intracellular cholesterol transport; lipid transport; phospholipid transport; sphingomyelin biosynthetic process; sterol transport; bile acid biosynthetic process; intermembrane lipid transfer; positive regulation of insulin secretion involved in cellular response to glucose stimulus; positive regulation of secretory granule organization
Cellular component: cytoplasm; cytosol; endoplasmic reticulum membrane; endoplasmic reticulum-trans-Golgi network membrane contact site; Golgi apparatus; Golgi membrane; membrane; perinuclear region of cytoplasm; trans-Golgi network; perinuclear endoplasmic reticulum; plasma membrane
Genetic constraint (gnomAD): Loss-of-function variants: 24 observed, 85.69 expected, observed/expected ratio (o/e) 0.28, 90% interval 0.2 to 0.39. The upper end of that interval is the gene's LOEUF score, 0.39, which puts it in group 1 of 6, group 1 being the genes least tolerant of losing a copy. Missense variants: 601 observed, 910.24 expected, observed/expected ratio (o/e) 0.66, 90% interval 0.62 to 0.71. Synonymous variants: 344 observed, 346.86 expected, observed/expected ratio (o/e) 0.99, 90% interval 0.91 to 1.08.
Homologues: Orthologues: chimpanzee OSBP (99% identical), macaque OSBP (99% identical), dog OSBP (98% identical), rabbit OSBP (97% identical), pig OSBP (97% identical), rat Osbp (97% identical), mouse Osbp (96% identical), guinea pig OSBP (87% identical), tropical clawed frog osbp (75% identical), zebrafish osbp (67% identical), Drosophila melanogaster CG3860 (20% identical), Caenorhabditis elegans obr-2 (17% identical). Paralogues in human: OSBP2 (58% identical), OSBPL3 (29% identical), OSBPL1A (28% identical), OSBPL6 (28% identical), OSBPL7 (28% identical), OSBPL2 (21% identical), OSBPL5 (19% identical), OSBPL8 (18% identical), OSBPL10 (18% identical), OSBPL9 (17% identical), OSBPL11 (16% identical).